RN7SL493P (RNA, 7SL, cytoplasmic 493, pseudogene)
Gene: Miscellaneous RNA gene on chromosome 16 (10,221,775 to 10,222,073, reverse strand). Ensembl gene ENSG00000266439.
Homologues: Orthologues: chimpanzee Metazoa_SRP (98% identical), macaque Metazoa_SRP (94% identical). Paralogues in human: RN7SL1 (87% identical), RN7SL2 (87% identical), RN7SL3 (87% identical), RN7SL444P (84% identical), RN7SL126P (84% identical), RN7SL127P (83% identical), RN7SL220P (83% identical), RN7SL660P (83% identical), RN7SL709P (82% identical), RN7SL478P (82% identical), RN7SL769P (82% identical), RN7SL301P (82% identical), and 705 more.